CYTH4 (cytohesin 4)
Description:
Promotes guanine-nucleotide exchange on ARF1 and ARF5. Promotes the activation of ARF factors through replacement of GDP with GTP.
Synonyms: CYT4; PSCD4; cytohesin-4; DJ63G5.1
Tractability: Antibody: UniProt places it where antibodies can reach, with high confidence; its Gene Ontology location is reachable by antibodies, with high confidence; the Human Protein Atlas places it where antibodies can reach. PROTAC: ubiquitination databases record sites on it; its protein half-life has been measured.
Gene: Protein-coding gene on chromosome 22 (37,282,027 to 37,315,346, forward strand). Ensembl gene ENSG00000100055.
Subcellular location: Cell membrane
Subcellular location (Human Protein Atlas): Plasma membrane; Centriolar satellite; Cytokinetic bridge; Cytosol
Pathways (Reactome):
Vesicle-mediated transport: Intra-Golgi traffic
Gene Ontology:
Molecular function: guanyl-nucleotide exchange factor activity; protein binding
Biological process: regulation of ARF protein signal transduction
Cellular component: plasma membrane; cytosol; Golgi membrane
Genetic constraint (gnomAD): Loss-of-function variants: 21 observed, 58.63 expected, observed/expected ratio (o/e) 0.36, 90% interval 0.25 to 0.52. The upper end of that interval is the gene's LOEUF score, 0.52, which puts it in group 2 of 6, group 1 being the genes least tolerant of losing a copy. Missense variants: 419 observed, 560.27 expected, observed/expected ratio (o/e) 0.75, 90% interval 0.69 to 0.81. Synonymous variants: 186 observed, 217.39 expected, observed/expected ratio (o/e) 0.86, 90% interval 0.76 to 0.97.
Homologues: Orthologues: chimpanzee CYTH4 (99% identical), macaque CYTH4 (99% identical), dog CYTH4 (95% identical), pig CYTH4 (95% identical), mouse Cyth4 (92% identical), rat Cyth4 (91% identical), rabbit CYTH4 (91% identical), guinea pig CYTH4 (91% identical), zebrafish cyth4b (71% identical), zebrafish cyth4a (65% identical), tropical clawed frog cyth4 (59% identical), Caenorhabditis elegans grp-1 (37% identical), and 1 more. Paralogues in human: CYTH3 (72% identical), CYTH1 (69% identical), CYTH2 (69% identical), ARFGEF1 (43% identical), ARFGEF2 (43% identical), GBF1 (36% identical), IQSEC1 (32% identical), IQSEC2 (29% identical), IQSEC3 (28% identical), PSD (23% identical), PSD2 (23% identical), MON2 (23% identical), and 3 more.
Diseases named in the same sentence as CYTH4 in open-access papers:
CYTH4 is named in the same sentence as 19 diseases in open-access papers, as found by Europe PMC text mining. Sharing a sentence is not in itself a finding about the gene and the disease. The quoted sentences say what the papers report.
bipolar disorder (2 papers, 2021 to 2024). A disorder of the brain that causes unusual shifts in mood, energy, activity levels and the ability to carry out day-to-day tasks. "Of 66 new DEGs, cytohesin 4 (CYTH4) is linked to bipolar disorder." (PMID 34497631, 2021). "The human CYTH4 has a primate-specific GTTT-repeat and longer repeats (7–9 vs <7) were found in healthy controls compared to patients with neurodegenerative disorders and bipolar disorder, while extremely long versions were seen in SCZ patients." (PMID 38263132, 2024).
melanoma (2 papers, 2023). A malignant, usually aggressive tumor composed of atypical, neoplastic melanocytes. "In addition to melanoma, CYTH4, AOAH, DENND1C, TBC1D10C, EPSTI1, SERPINB8, and GIMAP7 stratify responders and non-responders to ICB in other cancer types." (PMID 36588164, 2023). "CYTH4, DENND1C, AOAH, TBC1D10C, EPSTI1, GIMAP7, and FASL (FAS ligand) were novel predictors of ICB therapy and displayed high level of correlations with multiple immune checkpoints in melanoma and across 30 human cancers." (PMID 36588164, 2023).
ovarian carcinoma (2 papers, 2023 to 2024). A malignant neoplasm originating from the surface ovarian epithelium. "For instance, CYTH4 has been reported to be up-regulated and associated with worse survival in ovarian cancer and glioma." (PMID 38321024, 2024). "In the setting of ovarian carcinoma, CYTH4 expression is linked to tumor-infiltrating immune cell content and local expression of proinflammatory chemokines and antigen-presentation machinery in the TME." (PMID 37435077, 2023).
Alzheimer disease (1 paper, 2024). A progressive, neurodegenerative disease characterized by loss of function and death of nerve cells in several areas of the brain leading to loss of cognitive function such as memory and language. "Genes that were both selective for and highly expressed in the microglial cluster were Tgfbr1, Cyth4, Ikzf1, Dock2, and Inpp5d, many of which are associated with Alzheimer’s Disease (AD)." (PMID 38263132, 2024).
metastatic melanoma (1 paper, 2023). A melanoma that has spread from its primary site to another anatomic site. "CYTH4, DENND1C, AOAH, EPSTI1, and TBC1D10C expressions are upregulated in metastatic melanoma compared to primary tumors." (PMID 36588164, 2023).
tumor (3 papers, 2022 to 2025). "CYTH4, which regulates cell adhesion, migration, and immune responses, may promote tumor progression by enhancing motility and immune evasion." (PMID 41154345, 2025).
cancer (2 papers, 2020 to 2023). A tumor composed of atypical neoplastic, often pleomorphic cells that invade other tissues. "In a comparison to AXL with an established role in enhancing resistance to ICB, CYTH4, DENND1C, AOAH, EPSTI1, and TBC1D10C display a stronger correlation with immune checkpoints in human cancers." (PMID 36588164, 2023). "CYTH4, AOAH, DENND1C, TBC1D10C, EPSTI1, SERPINB8, and GIMAP7 are novel and robust individual genes in predicting resistance to ICB in multiple cancer types." (PMID 36588164, 2023). "Additionally, CYTH4, DENND1C, AOAH, EPSTI1, and TBC1D10C exhibit strong correlations with a set of immune checkpoints not only in SKCM but also across a spectrum of human cancers." (PMID 36588164, 2023).
CYTH4 also shares sentences with these, for which no sentence is quoted: atherosclerosis (1 paper); autoimmune disease (1); breast carcinoma (1); depression (1); glioma (1); infection (1); leiomyoma (1); liver fibrosis (1); lung carcinoma (1); multiple sclerosis (1); periodontitis (1); schistosomiasis (1).